AHRR (aryl hydrocarbon receptor repressor)
Diseases named in the same sentence as AHRR in open-access papers (continued):
Sharing a sentence is not in itself a finding about the gene and the disease.
tumor (continued). "AHRR is a putative tumor suppressor and regulates the activity of AHR, while NCOA2 functions as a transcriptional coactivator for nuclear hormone receptors." (PMID 35832542, 2022). "AhRR overexpression also decreased the number of palpable tumors at necropsy and reduced tumor multiplicity." (PMID 33763068, 2021). "Tumor growth was significantly enhanced after TCDD treatment only in wt mice while still suppressed in AhRR Tg mice." (PMID 33763068, 2021). "AhRR overexpression (PyMT/AhRR+) has a significant impact on tumor kinetics, increasing time to palpable tumor onset and decreasing incidence by the study censor date." (PMID 33763068, 2021). "AhRR is a putative tumor suppressor and is silenced in several cancer types, including breast, where its loss correlates with shorter patient survival." (PMID 33763068, 2021). "Our top hit is in the intronic region of the AHRR gene, located on chromosome 5 which is believed to possess several tumor suppressor genes." (PMID 34091768, 2021). "We have previously found methylation in tumour tissue is in the opposite direction to that observed in relation to smoking for AHRR (cg05575921), the CpG contributing most weight to the methylation score for smoking." (PMID 34583751, 2021). "The relationship between cigarette smoking and AHRR methylation, a known tumour suppressor, has been well documented in previous studies." (PMID 32745538, 2020). "In turn the tumor suppressor AHRR (aryl hydrocarbon receptor repressor) inhibits AHR and reduces inflammation and cancer progression." (PMID 31923221, 2020). "An analysis of 172 SHH tumours from the Taylor group in Toronto, confirmed both the increased expression of AHRR in SHH tumours, compared to other subgroups, as well as reduced survival of patients with high AHRR expression." (PMID 31924815, 2020). "LPS-stimulated tumor growth of EL4 cells was significantly reduced in AhRR Tg mice compared to wt mice." (PMID 31035533, 2019). "The current study was designed to test the tumor suppressive function of AhRR and to better understand the regulatory mechanisms of AhRR in inflammatory and cellular responses contributing to tumor promotion." (PMID 31035533, 2019). "To address the tumor-suppressive action of AhRR in vivo, we used a syngeneic murine tumor model to assess changes in tumor susceptibility associated with inflammation." (PMID 31035533, 2019). "The chromosomal region containing AHRR is frequently deleted in several types of human cancers and the AHRR promoter regions is also hypermethylated in several different tumour cell lines." (PMID 28681081, 2018). "Knockdown of the AHR repressor (AHRR), a putative tumor suppressor, increases anchorage-independent growth and tumor formation in lung cancer xenografts." (PMID 29735912, 2018). "AHRR has also been proposed to function independently of AHR particularly in its role as a tumor suppressor." (PMID 28681081, 2018). "Observational studies such as ours cannot clarify this, but the AHRR protein is located in the cell nucleus, and silencing of AHRR enhances tumour growth pleiotropically through increased Aryl Hydrocarbon Receptor activity." (PMID 28100713, 2017). "Recently, the AhRR has been shown to act as a tumor suppressor gene in several types of cancer cells, which has attracted the interest of an increasing number of cancer scientists." (PMID 26862745, 2016). "Beyond the role as a suppressor of the AhR signaling pathway, recent reports demonstrated the potential role of the AhRR in cancer biology acting as a tumor suppressor gene." (PMID 26862745, 2016). "A decrease in AHRR expression was detected in 13 (61.9%) of the 21 tumor tissue samples, compared with the expression in the matched adjacent non-tumor tissue samples (P = 0.004)." (PMID 22952704, 2012). "Recently, Haarmann-Stemmann T’s study proposed that AHRR expression in tumor cells inversely correlates with their angiogenic potential." (PMID 22952704, 2012).
tumor (continued). "The AHRR mRNA levels were significantly reduced in 27 (67.5%) tumor tissue samples, compared with the adjacent non-tumor tissue samples (P = 0.0423)." (PMID 22952704, 2012). "It was clearly showed that the expression status of AHRR was reduced in tumor tissue samples compared with that in matched adjacent non-tumor tissue samples by RT-qPCR (P = 0.0423) and western blotting analysis (P = 0.004)." (PMID 22952704, 2012). "These previous data consistently supported the assumption that AHRR plays as a tumor suppressor gene in several types of human cancer." (PMID 22952704, 2012). "Tumor cells with over expressed AHRR presented lower angiogenic potential, whereas tumor cells in which AHRR expression was blocked showed high angiogenic potential." (PMID 22952704, 2012). "Recently, AHRR has been proposed to function as a putative new tumor suppressor gene based on some relevant studies in multiple types of human cancers." (PMID 22952704, 2012). "Overall, 235 cases (57.3%) showed positive AHRR expression in the tumor tissue samples, whereas the remaining 175 cases (42.7%) displayed reduced cytoplasmic AHRR expression." (PMID 22952704, 2012). "In multivariate analysis, tumour AHRR and SFRP2 remained independent prognostic markers." (PMID 38361045, 2024). "However, there were no significant changes in the expression levels of AHR signaling pathway-related molecules, including AhR, AhRR, Cyp1a1, Cyp1a2, Cyp1b1 and Cox2, in tumor-infiltrating neutrophils from Arnt−/− mice." (PMID 36859266, 2023). "Although additional studies are warranted to confirm these results, our study suggests that AHRR hypomethylation may precede NHL as a response to tumor development." (PMID 37691855, 2023). "Evidence supports the notion that AhRR acts as a tumor suppressor." (PMID 37106727, 2023). "Notably, we demonstrate that AhRR overexpression in the PyMT background increases tumor latency and decreases tumor incidence and burden." (PMID 33763068, 2021). "We next generated PyMT/AhRR+ mice and followed tumor growth over time." (PMID 33763068, 2021). "This may be an outcome of decreased primary tumor burden in PyMT/AhRR+ mice and/or may reflect a decrease in functional metastatic capacity in PyMT/AhRR+ tumor cells." (PMID 33763068, 2021). "The AhRR may suppress extrinsic and tumor cell intrinsic oncogenic pathways in the tumor microenvironment to protect from chronic inflammation and tumorigenesis." (PMID 33763068, 2021). "Notwithstanding emerging evidence that AHRR may serve a protective role against TCDD-induced pathologies such as tumor growth and inflammation, very little is still known about its function in regulating AHR in different contexts." (PMID 34001975, 2021). "Previous studies have found that AhRR silencing increases tumor cell migration and invasion." (PMID 33763068, 2021). "As AhRR tends to play a significant role in suppressing inflammation, the downregulated AHRR expression may promote tumor growth." (PMID 33499346, 2021). "The interactions of O-GlcNAcylated TET with the AhR/AHRR and mitochondrial function in cells of the tumour microenvironment will be important to determine, especially as this has been proposed to underpin AhR-driven active DNA demethylation and thereby epigenetic memory." (PMID 33375613, 2020). "In vitro experiments with several different types of cancer cell lines showed that the AhRR may act as a tumor suppressor gene." (PMID 31035533, 2019). "While AhRR effectively blocks AhR signaling, several aspects of the mechanism of AhRR’s functions are poorly understood, including suppression of inflammatory responses and its putative role as a tumor suppressor." (PMID 31035533, 2019). "Furthermore, AhRR Tg mice were protected from LPS shock as well as LPS-induced tumor growth, which presents another important tumor suppressing function of AhRR since inflammatory processes are major contributing factors promoting cancer development." (PMID 31035533, 2019).
tumor (continued). "AHRR acts as a tumor suppressor gene in several types of cancer cells." (PMID 29320557, 2018). "Multivariate analysis using a Cox proportional hazards model assessed the prognostic value for MFS of the parameters found to be significant on univariate analysis, i.e., SBR histological grade, lymph node status, macroscopic tumor size, PR status and AHRR mRNA level." (PMID 29320557, 2018). "Thus, AHRR has been proposed to function as a putative new tumor suppressor gene in multiple types of human cancers." (PMID 28056099, 2017). "Additional studies are needed to investigate whether anti-inflammatory effects of AhRR may contribute to tumor suppression." (PMID 26862745, 2016). "Therefore, regulation of AHR activation via AHRR expression might indicate an important anti-oncogenic mechanism in primary tumours." (PMID 38361045, 2024). "Interestingly, knockdown of AhRR in normal human mammary epithelial cells resulted in anchorage-independent cell growth suggesting that the AhRR may function as a tumor suppressor gene." (PMID 36588678, 2022). "Thus the TCDD-independent yet AhRR-mediated tumor suppression is an important aspect, which may depend on endogenous ligands produced by the tumor microenvironment or tumor cells directly." (PMID 31035533, 2019). "However, AHRR has also been reported to function as a tumor suppressor independently of AHR." (PMID 28681081, 2018). "AHRR gene encodes two isoforms and the isoform without exon 8 has been reported to be the active isoform, which is the predominant form of AHRR expressed in multiple human tissues and human tumor cell lines." (PMID 22952704, 2012). "In the tumor RNA-seq dataset that contained AHRR expression levels, tumors with low MESH1 expression also displayed a high level of AHRR." (PMID 35273140, 2022). "The prognostic significance of lymph node status (p = 0.00025), macroscopic tumor size (p = 0.0062), SBR histological grade (p = 0.011) and AHRR mRNA level (p = 0.033) was maintained." (PMID 29320557, 2018). "However, as AHRR abrogates the growth and malignancy of various human cancers, a further elucidation of the link between AHRR and p27 may help to better understand AHRR’s tumor suppressive properties." (PMID 30013037, 2018). "The target of AHRR, the aryl hydrocarbon receptor (AHR) is a known protein that is a tumor suppressor, mediating detoxification of carcinogenic agents causing tobacco-related lung cancer." (PMID 25663950, 2015). "AHRR, a bHLH-PAS transcription factor, is located in chromosome 5p15.3 that has been proposed to contain one or more tumor suppressor genes." (PMID 22952704, 2012). "Thus, the levels of AhRR can be speculated to govern downregulation of CYP1B1 in tumor tissues." (PMID 22114726, 2011). "AHRR represses AHR and may act as a tumor suppressor; reduced expression was reported in malignant ovarian tissue, and it is hypermethylated in OvCa." (PMID 31923221, 2020). "On the other hand, the mechanism of the AhR Repressor (AhRR) acting as a tumor suppressor is poorly understood and has not been assessed in vivo." (PMID 31035533, 2019). "Furthermore, AHRR, the negative regulator of AHR signaling, functions as a tumor suppressor in multiple human tumors." (PMID 23420531, 2013). "Data revealed that the total AHRR mRNA expression and the AHRR isoform without exon 8 expression were significantly reduced in tumor tissues compared with the adjacent non-tumor tissues (P = 0.045 and 0.006, respectively)." (PMID 22952704, 2012). "According to this present study, the AHRR immunoreactivity presented significant differences between the tumor tissue samples and the adjacent non-tumor ones." (PMID 22952704, 2012). "Consistent with the total AHRR mRNA expression results, the AHRR isoform without exon 8 expression were significantly reduced in tumor tissues compared with the adjacent non-tumor tissues (P = 0.006)." (PMID 22952704, 2012).
tumor (continued). "However, how AhRR influences cancer progression is not well defined; in fact, it seems to act according to the tumor type, either as activator or as suppressor." (PMID 37511212, 2023). "We note that the growth of E0771 cells was suppressed in untreated AhRR transgenic mice suggesting that AhRR overexpression in the host may suppress tumor growth independent of exogenous and toxic AhR ligands." (PMID 33763068, 2021). "Interestingly, a number of binding sites for other tumor suppressors or cancer-related transcription factors, including E2F, EGR, KLF as well as STAT, were enriched or identified in regions uniquely bound by AHRR." (PMID 28681081, 2018). "Whether the tumour suppressor activity of AHRR is dependent or not on its ability to inhibit AHR is not fully understood." (PMID 28681081, 2018). "Such tumor suppressing actions of AhRR can no longer be explained by the existing theory alone." (PMID 26862745, 2016). "Cigarette smoking is also associated with genome wide changes inpulmonary macrophage DNA methylation, in particular at the aryl hydrocarbon receptor repressor (AHRR), a known tumor suppressor that may be critical in moderating AHR role in oncogenesisand altered immune function." (PMID 27891067, 2016). "Moreover, results demonstrated that the AHRR isoform without exon 8 was the predominant form either in tumor tissues (66.7%, 8/12) or in matched adjacent non-tumor tissues (100.0%, 12/12)." (PMID 22952704, 2012). "Besides, AHRR isoform without exon 8 was the predominant form either in tumor tissues (66.7%, 8/12) or in matched adjacent non-tumor tissues (100.0%, 12/12)." (PMID 22952704, 2012). "Moreover, data revealed that AHRR without exon 8 (the active isoform) was the predominant form either in tumor tissues (66.7%, 8/12) or in matched adjacent non-tumor tissues (100.0%, 12/12), and the mRNA level of this isoform was significantly reduced in tumor tissues (P = 0.006)." (PMID 22952704, 2012). "In contrast to AHRR and SFRP2 other markers did not maintain significance in multivariate analysis or could not be confirmed as being differentially expressed between primary and recurrent tumours on the protein level." (PMID 38361045, 2024).
cancer (42 papers, 2010 to 2026). A tumor composed of atypical neoplastic, often pleomorphic cells that invade other tissues. "Many previous studies reported that the changes of methylation sites in AHRR are associated with cancer, lung function, and low birth weight." (PMID 32000849, 2020). "Ranked quintiles of AHRR (cg05575921) methylation extent were associated with all baseline characteristics at the time blood collection for DNA extraction, except personal history of cancer." (PMID 28100713, 2017). "AHRR, the aryl-hydrocarbon receptor repressor gene, is a known cancer susceptibility gene." (PMID 27653773, 2016). "However, additional genes linked to cancer processes were found deregulated in this study including AHRR, C7, CLPTM1L, and MRPS30 involved in apoptosis, CDH6 in cell adhesion and CEP72 in the cell cycle." (PMID 22412903, 2012). "The results show that Aryl Hydrocarbon Receptor Repressor (AHRR) has hypomethylation due to PAH exposure, which is associated with oxidative stress and cancer risk." (PMID 40182693, 2025). "Here, we investigated AHRR methylation in non–Hodgkin lymphoma (NHL), a non–smoking-associated cancer." (PMID 37691855, 2023). "In cancer-diagnosed subjects, two probes corresponding to AHRR were found; one of them, cg05575921, overlapped with the results in the noncancer subset." (PMID 37509437, 2023). "For the cancer-diagnosed subset, cg05575921 for the AHRR gene and two probes cg21566642 and cg05951221 for intergenic regions." (PMID 37509437, 2023). "DNA methylation of CpG sites within the cancer-related genes AHRR, F2RL3, and B3GNTL1 was measured by pyrosequencing and relative mitochondrial DNA copy number and telomere length were measured by qPCR in whole-blood samples." (PMID 34570895, 2022). "Previous reports have shown that AhRR inhibits cell growth and resistance to apoptotic signals in human breast epithelial and cancer cells." (PMID 33763068, 2021). "In cancer cells, the AHRR-AHR feedback loop is interrupted by methylation of the AHRR promoter which blocks its expression." (PMID 31923221, 2020). "We observed increased AHRR expression in the normal bladder epithelial cells, as expected, however the opposite relationship in the cancer cell line." (PMID 24725556, 2014). "In the cancer-diagnosed subset, the genome-wide hypothesis-free analysis showed four differentially hypomethylated positions, one in the AHRR gene and three in intergenic regions." (PMID 37509437, 2023). "The absence of AHRR results in the induction of genes associated with tumorigenesis and cancer progression." (PMID 31923221, 2020). "Besides AHRR, MYO1G, and CYP1A1, highlighted for having large effect sizes, several other genes implicated by CpGs overlapping between lung and blood are also cancer related." (PMID 30872662, 2019). "Nevertheless, recent data are beginning to shed light on what may be a critical role, or the molecular mechanism, for the AHRR in cancer." (PMID 22952704, 2012). "Consequently, the IDO-Kyn-AhR signaling pathway provides a new target in cancer immunotherapy as discussed recently and AhRR may provide an important tool to inhibit this pathway." (PMID 33763068, 2021). "In contrast, treatment with 7k reduced the expression levels of AhR, AhRR, and IDO-1 in kynurenine-stimulated cancer cells in a dose-dependent manner." (PMID 41155994, 2025). "To determine whether the anticancer effects of 7k were mediated through AhR inhibition, we evaluated the expression of AhR downstream targets, including AhR, AhRR, and IDO-1, in kynurenine-stimulated cancer cells using qPCR analysis." (PMID 41155994, 2025). "Based on these results, we examined TCGA dataset using GEPIA2 web server to determine whether the expression of AhRR and PPP1R3C correlates with the expression of cancer stem cells markers." (PMID 37511212, 2023).
cancer (continued). "Furthermore, DMPs of AHRR, ADAMTS2, and FAM184 genes passed the sensitivity analysis for cell composition as follows: For the cancer-free subset, cg04450456 for FAM184B, cg02599361 for ADAMTS2." (PMID 37509437, 2023). "To investigate whether AhRR and PPP1R3C expression correlates with a worse outcome of patients in other cancers, we analyzed all TCGA datasets using GEPIA2 web server (accessed on 5 May 2023)." (PMID 37511212, 2023). "Several of these genes are related to cancer, including CD44, DST, GLS, GNAS, KIF1B and AHRR." (PMID 34086943, 2021). "In particular, our previous study of 1,000 healthy subjects from the EPIC and Norwegian Women and Cancer (NOWAC) cohorts indicated that smokers had 19% lower methylation levels at the AHRR CpG site cg05575921 compared with never-smokers." (PMID 26667048, 2015). "Finally, AhRR and PPP1R3C’s correlation with patients’ worse OS was identified in other cancers." (PMID 37511212, 2023). "In the cancer subset, DMR analysis found one region supported by more than one differential CpG for smokers in contrast to nonsmokers in the initial model corresponding to the AHRR gene." (PMID 37509437, 2023). "Therefore, it is possible that in some contexts AHRR mechanisms may be predominant as opposed to PARP7-DTX2-mediated degradation of AHR, and this may at least in part explain why certain cancer cell lines are resistant to PARP7 inhibition." (PMID 41326691, 2026).
cardiovascular disease (4 papers, 2016 to 2025). "The association between AHRR cg05575921 methylation and cardiovascular disease was also well addressed in Caucasians even in prospective studies." (PMID 35964014, 2022). "The association of AHRR methylation with CRP and incident CHD may highlight a connection between CRP and cardiovascular disease that is shared between cigarette smoking and independent mechanisms." (PMID 27955697, 2016).